ALB (albumin)
Diseases named in the same sentence as ALB in open-access papers (continued):
Sharing a sentence is not in itself a finding about the gene and the disease.
myocardial infarction (208 papers, 2005 to 2026). Gross necrosis of the myocardium, as a result of interruption of the blood supply to the area, as in coronary thrombosis. "Our research team first reported a dose–response relationship between low serum albumin levels and the risk of acute myocardial infarction in a Chinese Han population (HR = 1.79; 95% CI: 1.54–2.04)." (PMID 41377920, 2025). "Increasing evidence suggests that elevated BUN levels and decreased ALB levels are significantly linked to poorer prognosis in patients with acute myocardial infarction (AMI)." (PMID 40357038, 2025). "Low serum albumin has been associated with venous thromboembolism, myocardial infarction, stroke, and cardiovascular death." (PMID 41373420, 2025). "Serum albumin and body mass index (BMI, kg/m2) have been associated with outcomes following acute myocardial infarction (AMI)." (PMID 39728268, 2024). "In the “Framingham Offspring” study involving 4,506 individuals followed for 22 years, low serum albumin was an independent predictor of first myocardial infarction after adjustment for the usual risk factors." (PMID 38580915, 2024). "A previous study on patients with myocardial infarction reported that serum albumin levels were associated with increased mortality only in women." (PMID 39518469, 2024). "With relevance to the heart, it is suggested that low serum albumin levels in both males and females are associated with increased risk of myocardial infarction and linked to adverse outcomes after myocardial infarction." (PMID 37326614, 2023). "Several previous studies have reported that serum albumin has predictive value for STEMI, and decreased albumin level is associated with adverse outcomes after acute myocardial infarction." (PMID 37745131, 2023). "A 3-year follow-up study demonstrated a 4.11-fold increase in the risk of death in patients with acute myocardial infarction for each 1 g/dl decrease in albumin in the univariate model, consistent with our findings." (PMID 36523355, 2022). "Age, previous myocardial infarction, peripheral vascular disease, higher proteinuria and lower albumin were associated with future NFCVE." (PMID 35042473, 2022). "In the HAP group, we selected myocardial infarction, albumin, Cl, and chronic obstructive pulmonary disease as risk factors that collaboratively achieved an AUC of 0.6219." (PMID 34712677, 2021). "This was rather unexpected, as we had previously shown that renal function and/or urinary albumin excretion were associated with other macro-vascular disease-related outcomes such as myocardial infarction or major adverse cardiovascular events." (PMID 29879997, 2018). "In the trace urine albumin group, 4 cardiac deaths were caused by refractory heart failure (n = 1), acute myocardial infarction (n = 1), cardiac arrest (n = 1), or other cardiovascular causes (n = 1)." (PMID 25192238, 2014). "Our results demonstrated that haemoglobin concentration affected MACEs in patients with acute myocardial infarction, and that haemoglobin concentration was associated with age, albumin and creatinine." (PMID 21600038, 2011). "After matching, 2,374 patients with reduced albumin had higher risk of the composite outcome (HR 1.28, 95%CI 1.17-1.39), all-cause mortality (HR 1.72, 95%CI 1.50-1.96), and acute myocardial infarction (HR 1.74, 95%CI 1.28-2.35), compared to those with normal albumin." (PMID 42032112, 2026). "Eight statistically significant predictors were identified: age, sex, New York Heart Association cardiac function class III or IV, a history of myocardial infarction, and the albumin, triglycerides, N-terminal pro-b-type natriuretic peptide, and blood urea nitrogen levels." (PMID 38811919, 2024). "These include protein malnutrition, manifested as albumin (Alb) levels of less than 3.5 g/dl, which may be associated with death, myocardial infarction and sepsis." (PMID 34644766, 2021).
myocardial infarction (continued). "The long-term association between serum albumin-to-creatinine ratio (sACR) and poor patient outcomes in acute myocardial infarction (AMI) remains unclear." (PMID 32871964, 2020). "Microalbuminuria, defined as urinary excretion of albumin at a rate of 30–300 mg/24 h is a marker of endothelial dysfunction, vascular injury, and renal and cardiovascular disease, and is associated with increased risk for myocardial infarction." (PMID 30899260, 2019). "Low levels of albumin have been linked to critical illness and may be a risk factor for myocardial infarction." (PMID 24515975, 2015). "Albumin, an important acute-phase reactant, is used as an important biomarker in the diagnosis of various diseases such as pancreatitis and acute myocardial infarction." (PMID 41149135, 2025). "And, post-myocardial infarction metabolic disturbances accelerate protein catabolism, further depleting albumin levels." (PMID 40357038, 2025). "Increasing creatinine and the glutamine/glycine ratio (Gln/Gly) showed a higher risk of a future myocardial infarction, while higher cholesteryl esters in large HDL (L-HDL-CE) and albumin levels conferred protection." (PMID 40973818, 2025). "In recent years, several clinical studies have demonstrated a correlation between elevated BUN levels and decreased ALB and poor prognosis in patients with cardiovascular disease, including acute coronary syndrome and acute myocardial infarction." (PMID 40980177, 2025). "In conclusion, our study provides novel insights into the dynamic role of albumin changes in the prognosis of older patients with acute myocardial infarction." (PMID 39902029, 2024). "As the most serious type of CHD, myocardial infarction was also related to serum albumin levels, which clinically significant." (PMID 36635398, 2023). "Red blood cell distribution width (RDW) and albumin level were considered to be related to the prognosis of patients with acute myocardial infarction (AMI)." (PMID 36737704, 2023). "Other studies found that serum albumin levels and cardiovascular disease risk, including CHD, such as angina pectoris and myocardial infarction, were also inter-related In Europeans10,15." (PMID 36635398, 2023). "Some studies have found that low serum albumin levels increased the incidence of cardiovascular diseases, such as myocardial infarction." (PMID 36635398, 2023). "This study also concluded that lower blood albumin levels and higher cTnI levels were significant predictors of myocardial infarction in individuals." (PMID 36808769, 2023). "Recently, increased levels of recruited macrophages and AGE-albumin were observed in the hearts of humans and animals with acute myocardial infarction." (PMID 36555270, 2022). "In this study, we evaluated the utility of neutrophil percentage-to-albumin ratio (NPAR) in predicting in critically ill patients with acute myocardial infarction (AMI)." (PMID 35300600, 2022). "A decreased admission serum albumin level has been found to be an independent predictor of long-term mortality in hospital survivors of acute myocardial infarction." (PMID 36615064, 2022). "The primary endpoint, a composite of cardiovascular events (CVEs) including CV death, myocardial infarction, ischemic stroke and coronary revascularization, was analysed according to baseline values of serum albumin (≥ or < 3.5 g/dL)." (PMID 34239442, 2021). "The trial was terminated after 434 patients were enrolled, for safety reasons due to higher 90-day mortality rate and increased serious adverse events (a.o. pulmonary edema, acute coronary syndrome and myocardial infarction) in the Albumin group." (PMID 34666786, 2021). "Low serum albumin (LSA) on admission for acute myocardial infarction (AMI) is related to adverse in-hospital outcomes." (PMID 32872477, 2020). "In diseases such as atherosclerosis and myocardial infarction, an increase in albumin leakage is expected due to acute endothelial damage and later microvessel formation." (PMID 29735362, 2018).
myocardial infarction (continued). "Risk burdens of modifiable risk factors incorporating lipoprotein (a) (Lp(a)) and low serum albumin (LSA) concentrations for first incident acute myocardial infarction (AMI) haven’t been studied previously." (PMID 27748452, 2016). "One potential clinical application of the technique for calculating albumin concentration relates to myocardial infarction, therefore a feasibility assessment using human cardiac images was considered relevant." (PMID 24515975, 2015). "Cardiac death occurred in 11 patients in the positive urine albumin group due to refractory heart failure (n = 6), acute myocardial infarction (n = 1), cardiac arrest (n = 1), or other cardiovascular causes (n = 3)." (PMID 25192238, 2014). "Five weeks after myocardial infarction (MI), a midline thoracotomy was performed and 50 μL of 0.5% bovine serum albumin for group 1, 2 × 106 cells in 0.5% BSA for group 2, 50 μL of fibrin for group 3, or 2 × 106 cells in fibrin for group 4 was intramuscularly injected into the infarct scar." (PMID 41301140, 2025). "Age, sex, NYHA class, a history of myocardial infarction (MI), and the albumin, triglyceride, N-terminal brain natriuretic peptide (NT-ProBNP), blood urea nitrogen (BUN) significantly differed between the survivors and deceased patients in the modeling and validation groups." (PMID 38811919, 2024). "In the overall cohort, compared with new users of DPP4i, new users of GLP1a were more likely to have higher urine-to-albumin creatinine ratio levels, whereas new users of SGLT2i were more likely to have a history of myocardial infarction and higher eGFR levels." (PMID 38993538, 2024). "However, the correlation between albumin-corrected anion gap (ACAG) and 30 d all-cause mortality of intensive care patients with acute myocardial infarction (AMI) is unclear." (PMID 37118662, 2023). "Similarly, a retrospective study of 1,424 patients with acute myocardial infarction showed a higher incidence of in-hospital MACE in patients with low serum albumin levels." (PMID 37283624, 2023). "Recently, some researches have showed a new inflammatory marker, albumin to fibrinogen ratio (AFR), was associated with adverse outcomes in many diseases, including peritonitis-induced sepsis, myocardial infarction, ischemic stroke, gastric cancer, and knee synovitis." (PMID 37974066, 2023). "There were 17 independent risk factors: age, comorbidity of myocardial infarction, cerebrovascular disease, renal disease, metastatic solid tumor, heart rate, respiratory rate, O2 saturation, MCHC, RDW, albumin, total bilirubin, bicarbonate, lactate, vasopressor use, CRRT, and ventilation." (PMID 36465642, 2022). "Moreover, analysis of serum albumin level by continuous variables in patients with first-onset acute myocardial infarction, each 1 g/dl albumin level reduction exhibited a 66 and 47% higher risk of all-cause mortality and cardiovascular death, respectively." (PMID 31815281, 2020). "Furthermore, it was tested whether human serum albumin (HSA) or MgCit can be applied to decrease the serum calcification propensity in 100 patients with myocardial infarction." (PMID 41373420, 2025). "Similarly, in a separate study involving 7,647 individuals, low serum albumin displayed a robust and independent association with the occurrence of a first episode of myocardial infarction, irrespective of traditional risk factors." (PMID 38580915, 2024). "Furthermore, many factors can affect albumin levels and/or the incidence of myocardial infarction." (PMID 38773489, 2024). "Although the neutrophil percentage-to-albumin ratio (NPAR) has shown prognostic value in multiple clinical conditions, its prognostic accuracy for myocardial infarction (MI) patients receiving intensive care has yet to be clearly defined." (PMID 41488461, 2025). "Recently, the serum BUN to serum albumin ratio (BAR) has emerged as a useful prognostic indicator of acute kidney injury, acute pulmonary embolism, acute myocardial infarction, and sepsis." (PMID 41171733, 2025).
myocardial infarction (continued). "CRP and serum albumin are the commonly used parameters, and several studies have shown a strong link between these inflammatory markers and the severity of CAD among myocardial infarction (MI) patients." (PMID 40922854, 2025). "Thrombolysis in myocardial infarction (TIMI) scores were calculated, and serum C-reactive protein and albumin levels were measured within 24 hours of admission." (PMID 41018414, 2025). "The Moderate group had a lower baseline thrombolysis in myocardial infarction (TIMI)flow grade and the serum albumin level was lower (40.7 vs 40.3 vs 34.8, p = 0.001) than the other two groups (50.7 vs 45.9 vs 91.7, p =0.014)." (PMID 39077570, 2023). "In addition, low albumin level is associated with increased glycated albumin and HbA1c levels in patients with DM, some of whom may have experienced non-fatal myocardial infarction." (PMID 37745131, 2023). "We aimed to find sensitive predictive indicators to identify high‐risk FWR patients by exploring the predictive values of neutrophil percentage‐to‐albumin ratio (NPAR) and monocyte‐to‐lymphocyte ratio (MLR) on patients with acute myocardial infarction (AMI)." (PMID 34820903, 2022). "At baseline, 564 (6.7%) subjects had CVD (defined as a myocardial infarction and/or cerebrovascular accident) and 1361 (16.2%) subjects had CKD (defined as eGFR < 60 ml/min/1.73m2 and/or urinary albumin excretion (UAE) > 30 mg/24 h)." (PMID 33883651, 2021). "Identification of abnormal extravascular albumin distribution correlating to increased capillary leakage may have several applications, including early indication of disease progression or treatment response in tumor angiogenesis, or assessment of reperfused myocardial infarction." (PMID 24515975, 2015). "Long-acting GLP-1 mimetics, such as domain antibodies to serum albumin, can sustain the activation of GLP-1R and reduce myocardial infarct size and injury in acute coronary syndrome." (PMID 25855361, 2015). "Additionally, a prospective study demonstrated that the albumin-CRP ratio, which integrates albumin and CRP, has superior predictive ability for in-hospital mortality in acute myocardial infarction patients compared to CRP or albumin alone." (PMID 41607462, 2026). "Our previous studies demonstrated that the Glasgow Prognostic Score (GPS), which utilizes serum albumin (ALB) and serum C-reactive protein (CRP) levels, is a straightforward and potent method for assessing the prognosis of patients experiencing acute myocardial infarction." (PMID 39987233, 2025). "Within 24 h after myocardial infarction surgery, elevated CTI was associated with decreased albumin and prealbumin levels, but not TBIL/ALB ratio." (PMID 41458520, 2025). "An early myocardial infarction is characterized by a brief and transient rise in urine albumin, especially microalbuminuria, without functional or structural renal damage." (PMID 39364405, 2024). "In comparison with the group without myocardial infarction, the myocardial infarction group exhibited lower levels of albumin, total cholesterol, total protein, erythrocyte count, hemoglobin, platelet count, and alcohol consumption." (PMID 39624218, 2024). "Relative to the low-risk group, the medium- and high-risk groups were noticeably different in age, sex, weight, diastolic blood pressure, time of onset, myocardial infarction site, Hb, ERY, HCT, MCHC, SD, ALB, A/G, TC, TG, LDL, blood urea nitrogen, PT, and PtA (all P < 0.05)." (PMID 38093222, 2023). "In the PREVEND study of 7579 non-diabetic, non-hypertensive individuals, MA, defined as urinary albumin excretion 20–200 mg/L, was also linked to ECG evidence of either myocardial infarction or ischemia." (PMID 36227142, 2022). "Based on an average follow-up of 7.5 years, low serum albumin levels together with high CRP levels were shown to be associated with long-term adverse cardiac events (all-cause death and nonfatal myocardial infarction)." (PMID 33453709, 2021).
myocardial infarction (continued). "In the negative urine albumin group, 16 cardiac deaths were attributed to refractory heart failure (n = 6), acute myocardial infarction (n = 6), sudden death (n = 2), or other cardiovascular causes (n = 2)." (PMID 25192238, 2014). "We aimed to assess the levels of ischemia-modified albumin (IMA) and also to study its sensitivity and specificity in comparison with cardiac troponin T/troponin I and electrocardiogram (ECG) (alone and in combination) in the diagnosis of acute myocardial infarction." (PMID 37779796, 2023). "In addition, recombinant human albumin alone at a dose of 2.7 mg/kg was administered to the rats as a control experiment without having any effect on myocardial infarct size (data not shown), further confirming the infarct size-limiting effect of albiglutide." (PMID 21887274, 2011). "The C-reactive protein-to-albumin ratio (CAR) serves as a composite marker reflecting both systemic inflammation and nutritional status and may enhance prognostic accuracy in myocardial infarction (MI)." (PMID 41018414, 2025). "NSTEMI, non-ST elevated myocardial infarction; STEMI, ST elevated myocardial infarction; BMI, body mass index, LDL, low-density lipoprotein, CKMB, creatine kinas-MB; WBC, whole blood cell count; IMA, ischemia modified albumin; MDA, malondialdehyde; SOD, superoxide dismutase." (PMID 34177373, 2021).